HMGB1 (high mobility group box 1)
Diseases named in the same sentence as HMGB1 in open-access papers (continued):
Sharing a sentence is not in itself a finding about the gene and the disease.
tumor (continued). "As one potential mediator of these pathological features, the role of HMGB1 in tumor development and progression is apparent." (PMID 31731454, 2019). "On the other hand, HMGB1 over expressed in tumor cells is also released and enhances inflammation by activating dendritic cells and tumor-specific T cells." (PMID 31058025, 2019). "Local dendritic cells were shown to respond to HMGB1 by enhancing antigen processing and presentation of tumor specific antigens to T cells." (PMID 31015520, 2019). "Tumor cell-derived HMGB1 increases the absolute numbers of Tregs in the spleen and draining lymph nodes of tumor-bearing mice, while also stimulating Tregs to produce IL-10 and suppress T cell activation." (PMID 31379812, 2019). "In this study, we aimed to determine the signaling pathway of extracellular HMGB1 and its roles in tumor proliferation in both ABC-DLBCL and GCB-DLBCL." (PMID 30988279, 2019). "High mobility group box 1 (HMGB1), one damage associated molecular patterns (DAMP), is associated with either anti- or pro-tumor effects depending on the microenvironment and/or model under investigation." (PMID 30744691, 2019). "We observed that the combination of radiation with inhibition of the extracellular HMGB1 using GLZ resulted in a two folds reduction in tumor volume compared to radiation alone." (PMID 31015520, 2019). "A massive release of HMGB1, induced by chemotherapy, will stimulate the immune system such that an anti-tumor response is induced, as well as a pro-tumor effect at the long term." (PMID 30650521, 2019). "The radiosensitization effect of HMGB1 inhibition is likely immune mediated as observed by the marked changes in the tumor immune landscape and the significant decrease in the frequency of MDSCs and TAMs when combining HMGB1 inhibition and radiation." (PMID 31015520, 2019). "The subsequent release of DAMPs including HMGB-1 and ATP from tumor cells by the action of NPs provided immunogenic stimuli to the antigen presenting DC." (PMID 31695807, 2019). "Tumor growth in both flanks was markedly inhibited by HMGB1 (instead of tumor lysate), injected to the right-side tumor, followed by intravenous injection of eMIP." (PMID 31058025, 2019). "This strategy for HMGB1 inhibition ensures near complete elimination of actively and passively released HMGB1 within the tumor microenvironment." (PMID 31015520, 2019). "Several reports have addressed the relationship between the overexpression of HMGB1 with the tumor progression in different cancer types, including lung, osteosarcoma, cholangiocarcinoma, colorectal, and liver cancer." (PMID 31779212, 2019). "HMGB1-dependent TLR4/MyD88/TRIF activation leads to T cell activation in response to dying tumor cells." (PMID 30941308, 2019). "Regarding immunogenicity, anthracyclines, oxaliplatin, mafosfamide, bortezomib, and some other types of chemotherapy agents are effective in inducing CRT and HSP exposure, as well as ATP secretion and HMGB1 release from various tumor cells including leukemias." (PMID 31649875, 2019). "We previously reported that treatment-mediated release of HMGB1 has function to stimulate immune function of dendritic and T-cells for eliminating tumor cells." (PMID 30988279, 2019). "In fact, HMGB1 can either be passively released or actively secreted from several cell types, including different immune and tumor cells." (PMID 31779212, 2019). "We showed that mEHT was effective in producing an immunogenic milieu by triggering the release of ATP, HMGB1, and hsp70, which can promote the anti-tumor immune response." (PMID 31426515, 2019). "Later, researchers identified an endogenous TLR2 agonist called high-mobility-group box 1 (HMGB1), wich is released by dying tumor cells as a result of tumor cell killing." (PMID 31240216, 2019). "In terms of the mechanism, NNT-AS1 acts as a ceRNA on miR-496, thereby reversing the tumor-suppressive influence of miR-496 on HMGB1 expression." (PMID 31848324, 2019).
tumor (continued). "It has also been reported that high mobility group box-1 protein (HMGB1) increased the expression of P-gp, thereby promoting drug resistance and the proliferation and invasion of tumor cells." (PMID 31312250, 2019). "Here, we report for the first time that treatment with EP significantly inhibited DLBCL tumor growth in vitro and in vivo by blockade of HMGB1-mediated Src/ERK signaling pathway and cell cycle G1 to S phase transition." (PMID 30988279, 2019). "Among several NSCLC chemotherapeutics (paclitaxel, docetaxel, carboplatin, mitoxantrone), they found that the combination of oxaliplatin and cyclophosphamide significantly increased nuclear HMGB1 staining in tumor nodules." (PMID 31191545, 2019). "In this study, irradiated tumor cells showed different levels of γH2AX protein expression, and HMGB1 KO tumor cells exerted severe DNA damage." (PMID 29844348, 2018). "Taken together, these results indicated that secretion of HMGB1 from dying tumor cells promotes ERK-mediated Drp1 phosphorylation, which contributes to autophagy and chemoresistance following chemotherapeutic treatment." (PMID 30258050, 2018). "HMGB1/RAGE axis signaling also increases phosphorylation of ERK1/2 to induce tumor cell invasion and metastasis." (PMID 29636841, 2018). "As revealed by western blotting, HT29 and HeLa cells displayed elevated level of ERK signaling activation after irradiation, in which HMGB1 KO tumor cells rendered less visible." (PMID 29844348, 2018). "Our quantitative RT-PCR and Western blot analyses revealed that relative HMGB1 gene expressions at both transcriptional and translational levels were significantly higher in tumor tissues compared with its normal control tissues (P<0.001)." (PMID 29899164, 2018). "Secretomic profiling, bioinformatics, and functional studies revealed that tumor cell-derived high-mobility group box 1 (HMGB1) protein was a major contributor of Treg differentiation within the NB TME." (PMID 30643519, 2018). "HMGB1 levels in mouse sera significantly correlated with HIF-1 alpha expression in the corresponding PDX tumor tissues." (PMID 30123419, 2018). "Taken together, these results suggest that GC-Ex delivers HMGB1 to neutrophils and induces pro-tumor activation through TLR4/NF-κB signaling." (PMID 30292233, 2018). "After treatment with Dex, the tumor burden was lower in HMGB1 knockdown mice than in control mice (p < 0.05)." (PMID 30157958, 2018). "ICD is typically characterized by expression and/or release of damage-associated molecular patterns (DAMPs) including ATP, a “find me” signal for monocytes, and high mobility group box 1 (HMGB1), promoting the presentation of tumor-associated antigens by DCs." (PMID 29849952, 2018). "Taken together, these results indicated that the extracellular HMGB1 promotes ERK activation-mediated Drp1 phosphorylation resulting in tumor growth and chemoresistance via RAGE." (PMID 30258050, 2018). "In vivo, xenograft models showed that after Dex treatment, the tumor burden of HMGB1-knockdown mice was decreased compared with that of control mice." (PMID 30157958, 2018). "High-mobility group box 1 (HMGB1) is an important enzyme that is highly expressed in tumor cells and has a subcellular localization that is dependent on its acetylation or oxidative state." (PMID 30279967, 2018). "Similar induction was observed in HMGB1 WT tumor cells treated by irradiated HMGB1 WT or KO cell culture supernatant, although the activation timing and intensity were slightly different." (PMID 29844348, 2018). "Binding to RAGE, HMGB1 enhances cell migration and tumor metastasis, thereby promoting cancer development." (PMID 29651425, 2018). "Our in vivo experiments showed that after Dex treatment, the HMGB1-knockdown mice had a lower tumor burden than the control mice." (PMID 30157958, 2018).
tumor (continued). "These agents promote the release of tumor antigens in conjunction with the release of signals that activate APCs, including ATP, high mobility group box-1 (HMGB1) and interferon-β (IFNβ), and the exposure of calreticulin on the surface of tumor cells." (PMID 30208166, 2018). "Especially for RCC, expression of HMGB1 was significantly higher in the tumor than in the peritumoral tissue." (PMID 30123419, 2018). "Our study was the first attempt that simultaneously compared the expression of the mRNA and protein of HMGB1 in the blood and tumor tissue of HNSCC patients and healthy controls." (PMID 30245980, 2018). "The changes in the relative levels of protein expression of activated forms of ERK in irradiated HMGB1 WT and KO tumor cells, including HMGB1 WT tumor cells treated by supernatant derived from irradiated HMGB1 WT and KO tumor cells." (PMID 29844348, 2018). "Of note, tumor cell lines exhibited higher HMGB1 protein levels despite having lower levels of mRNA." (PMID 29472602, 2018). "With this background in mind, the present study aimed to evaluate the expression of HMGB1 protein and mRNA in the tumor tissues and normal margin tissues of HNSCC patients and the blood samples of healthy individuals with matched age and gender." (PMID 30245980, 2018). "Extracellular HMGB1 acts as a pro-tumor protein due to its cytokine, chemokine, and growth factor action, whereas intracellular HMGB1 increases drug resistance due to its proautophagic activity." (PMID 30245980, 2018). "The exact mechanism between tumor hypoxia signaling and intra-/extracellular HMGB1 levels needs to be further examined." (PMID 30123419, 2018). "As a matter of fact, HMGB1 expression is enhancive in many types of cancer, which interrelates with tumor malignancy and poor prognosis." (PMID 29844348, 2018). "Intracellular HMGB1 has been shown to play an important role in maintaining genome stability and autophagy activity during tumor growth; thus, it seems to act as an antitumor protein." (PMID 29636841, 2018). "Determining if HMGB1 modulation can enhance various cancer treatment modalities warrants further investigation and will likely vary on the cellular profile of the tumor microenvironment and tumor cell type itself." (PMID 29543735, 2018). "To further confirm the link between HMGB1 and apoptosis, we established a xenograft tumor model by injecting 1 × 105 Panc-1 cancer cells subcutaneously into the right flank of the nude mouse." (PMID 29615080, 2018). "Due to HMGB1 playing a key role in tumor progression, we analyzed the amount of HMGB1 in 20 HCC tissue samples and their paired peritumor liver samples by qPCR and also analyzed four paired samples by western blotting." (PMID 30526680, 2018). "In the experimental setting, inhibition of HMGB1 release diminish ATP production and retard tumor growth." (PMID 30049847, 2018). "As the best-known and characterized DAMP molecule, HMGB1 stimulates inflammation and angiogenesis to promote tumor progression." (PMID 29636841, 2018). "HMGB1 is an important component of the tumor microenvironment induced by chemotherapy or radiotherapy." (PMID 29615080, 2018). "As the findings of the present study indicated, the level of HMGB1 protein was positively correlated with mRNA levels in the tumor samples." (PMID 30245980, 2018). "According to the results the expression levels of HMGB1 protein and mRNA were significantly higher in the tumor tissue than in the normal margin tissues (P<0.01)." (PMID 30245980, 2018). "Generally chemotherapy induces immunogenic cell death which leads to the recruitment of immune-related cells including TILs by releasing high-mobility group box 1 protein (HMGB1) that promotes the cross-presentation of tumor derived antigens to T cells." (PMID 30344939, 2018). "High mobility group protein B1 (HMGB1) is a protein released by tumor cells in response to the cytotoxic effects of chemotherapeutic agents." (PMID 29282893, 2018).
tumor (continued). "The importance of HMGB1 in tumor repopulation was further confirmed by knocking out the expression and function of HMGB1 by CRISPR/Cas9 technology in HT29 and HeLa cells." (PMID 29844348, 2018). "Recent studies have reported a significant increase in the expression level of HMGB1 protein in multiple tumor tissues." (PMID 30245980, 2018). "The results were also indicative of the decreased differentiation level of tumor cells by increasing the HMGB1." (PMID 30245980, 2018). "According to the results, HMGB1 expression was significantly higher in the tumor tissues, compared to that in the normal tissues (P<0.01)." (PMID 30245980, 2018). "We demonstrated that HMGB1 released from irradiated tumor cells promoted surviving tumor cell proliferation via HMGB1/RAGE/ERK signaling pathway." (PMID 29844348, 2018). "Inhibition of HMGB1/TLR4 interaction suppressed GC-Ex-induced pro-tumor activation of neutrophils, supporting that HMGB1 is a key factor for the roles of GC-Ex." (PMID 30292233, 2018). "Expression of HMGB1 is upregulated in many cancer types and there are preliminary data available that HMGB1 enhances tumor growth." (PMID 30123419, 2018). "The role of elevated HMGB1 levels in cancers is paradoxical because current research has demonstrated that HMGB1 has both tumor-promoting and suppressing effects in cancer progression." (PMID 29728635, 2018). "In the downstream of the miR-1284/HMGB1 signal axis, expression of the genes associated with epithelial–mesenchymal transition (EMT), which enables tumor cells to migrate and invade, was measured with Western blotting." (PMID 29899164, 2018). "HCC releases DAMP proteins, such as HMGB1, which interact with their receptors, triggering a proinflammatory signaling cascade that contributes to tumor progression." (PMID 29651425, 2018). "Radiotherapy can lead to the release of tumor antigens and/or DAMPs, such as calreticulin, HMGB1, or ATP, which can activate both the innate and adaptive immune system, and enhance tumor-cell immunogenicity." (PMID 29482595, 2018). "For instance HMGB1, calreticulin, and viral/cellular DNA can be released in the tumor microenvironment and elicit immune-cell recruitment." (PMID 30514385, 2018). "Following chemotherapy treatment, the release of HMGB1 is induced, and HMGB1 can exert autocrine or paracrine effects that activate Drp1 and lead to chemoresistance and tumor recurrence." (PMID 30258050, 2018). "HMGB1, once released from dying tumor cells, also impacts on antigen processing and presentation by DC." (PMID 29462947, 2018). "The release of HMGB1 by necrotic cells can enhance inflammatory responses, tumor formation, and metastasis through the release of proinflammatory cytokines by activating proinflammatory signaling pathways, including NF-κB and inflammasome pathways." (PMID 29636841, 2018). "Immunoblotting results from resected tumor tissues also revealed high HMGB1 level, active ERK1/2 and phospho-Drp1S616 in LoVoOXR group." (PMID 30258050, 2018). "We found that silencing of TLR2, but not RAGE, TLR4, or CD24, inhibited the migratory ability of the living cancer cells, indicating that HMGB1 regulates tumor cell invasion through TLR2 in vitro." (PMID 29615080, 2018). "We also show that HMGB1 depleted HSV1716-conditioned media is less toxic to naïve tumor cells compared to HSV1716gfp-conditioned media with abundant HMGB1." (PMID 29543735, 2018). "In the present study, we used tumor tissue microarrays to characterize an independent cohort of 90 NSCLC patients for the expression of HMGB1." (PMID 29850505, 2018). "As HMGB1 is reported as a necrosis marker, we analyzed the amount of HMGB1 released in tumor cell culture medium at different time points post irradiation." (PMID 29844348, 2018). "In contrast, there is evidence that chemotherapeutic drug-induced HMGB1 can mediate the activation of innate immunity and tumor clearance." (PMID 30258050, 2018).
tumor (continued). "HMGB1 was recently reported to be expressed on tumor-derived exosomes and packaged in human AECD exosomes." (PMID 30526680, 2018). "HMGB1 contributes to inflammation, immunity, metastasis, metabolism, apoptosis, and autophagy during tumor development and cancer therapy." (PMID 29636841, 2018). "For example, tumor secreted factors, including lactate and HMGB1, induced macrophage polarization to M2 type, but these factors also induced IL-1β production in the cells." (PMID 30586442, 2018). "At the same time, we also analyzed the expression of HMGB1 in the nucleus and cytoplasm of irradiated tumor cells at different time point after irradiation respectively." (PMID 29844348, 2018). "An early study showed that HMGB1 inhibited MSC proliferation while the opposite effect was evoked by stimulating MSCs with HMGB1 released from necrotic tumor cells." (PMID 29615103, 2018). "Using CRT exposure and HMGB1 release as surrogate markers for drug-induced tumor cell immunogenicity, we found that OxP treatment indeed induced immunogenic effects on CT26-FL3 cells." (PMID 29884866, 2018). "Release of High Mobility Group Box 1 (HMGB1) from the necrotic tumor cells can activate tumor-resident dendritic cells resulting in the induction of a tumor-specific T cell response." (PMID 29694419, 2018). "As an immune-activating factor, HMGB1 released from necrotic tumor cells binds to Toll-like receptor 4 (TLR4) expressed by dendritic cells (DCs) to promote antigen presentation and also activates macrophage TNF release and thus activates antitumor immunity." (PMID 30643519, 2018). "Tumor radiation results in upregulation or generation of tumor-associated antigens (TAA) and DAMPs including HMGB1 and HSPs, which served as agonists of TLRs and thus primed “immunogenic cell death” via TLR-mediated signaling pathways." (PMID 29958545, 2018). "When administered to TLR4-expressing DC in vitro, HMGB1 augments the expression of pro-IL-1β and prevents the lysosomal degradation of engulfed tumor antigens, which is a major prerequisite for efficient cross-presentation." (PMID 29462947, 2018). "Serum HMGB1 levels were significantly higher in a subset of the PDX collection, which exhibited slower tumor growth during subsequent passages than tumors with low HMGB1 serum levels." (PMID 30123419, 2018). "Recently, High mobility group box 1 (HMGB1) was demonstrated to be expressed on tumor-derived exosomal membranes and packaged in human amnion epithelial cell-derived exosomes (AECD-exosomes)." (PMID 30526680, 2018). "The peripheral blood and tumor tissue RNA samples of 44 patients were analyzed by quantitative RT-PCR for HMGB1 gene." (PMID 30245980, 2018). "In order to illustrate HMGB1 releasing is a common appearance during cytotoxic therapy, we detected HMGB1 in tumor cell medium treated by chemotherapy." (PMID 29844348, 2018). "When HMGB1 is released from dying tumour cells, protective immunity is stimulated through toll-like receptor (TLR) signalling." (PMID 30261606, 2018). "For example, acting as an anti-tumor factor, intracellular HMGB1 sustains autophagy and stabilizes the genome." (PMID 29728635, 2018). "(A) Flow cytometry analysis of HMGB1 expression by tumor-derived exosomes and hepatocyte-derived exosomes." (PMID 30526680, 2018). "In RCCs with high HMGB1 levels, bevacizumab induced a delay in tumor growth (RXF 1114, 1393, 2282, 2359 and 2395), stable disease (RXF 488, 739 and 2521) or even remission (RXF 616, 2264 and 2717)." (PMID 30123419, 2018). "Apart from being released by tumor cells, HMGB1 is also secreted by macrophages and monocytes upon stimulation with cytokines in order to promote immunogenic responses." (PMID 30123419, 2018). "Autophagy can also contribute to inhibition of the metastatic process regulating the release of immunomodulatory factors HMGB1 from tumor cells." (PMID 29783720, 2018).